EMB (embigin)
Description:
Plays a role in the outgrowth of motoneurons and in the formation of neuromuscular junctions. Following muscle denervation, promotes nerve terminal sprouting and the formation of additional acetylcholine receptor clusters at synaptic sites without affecting terminal Schwann cell number or morphology. Delays the retraction of terminal sprouts following re-innervation of denervated endplates. May play a role in targeting the monocarboxylate transporters SLC16A1, SLC16A6 and SLC16A7 to the cell membrane (By similarity).
Synonyms: MGC71745; GP70
Tractability: Antibody: its Gene Ontology location is reachable by antibodies, with high confidence; UniProt places it where antibodies can reach, with medium confidence; UniProt predicts a signal peptide or a membrane-spanning region. PROTAC: ubiquitination databases record sites on it; its protein half-life has been measured.
Gene: Protein-coding gene on chromosome 5 (50,396,192 to 50,443,248, reverse strand). Ensembl gene ENSG00000170571.
Subcellular location: Cell membrane; Synapse
Pathways (Reactome):
Transport of small molecules: Proton-coupled monocarboxylate transport
Gene Ontology:
Molecular function: protein binding; cell-cell adhesion mediator activity
Biological process: axon guidance; dendrite self-avoidance; homophilic cell-cell adhesion; plasma membrane lactate transport; cell adhesion
Cellular component: axon; plasma membrane; synapse
Genetic constraint (gnomAD): Loss-of-function variants: 13 observed, 23.25 expected, observed/expected ratio (o/e) 0.56, 90% interval 0.36 to 0.89. The upper end of that interval is the gene's LOEUF score, 0.89, which puts it in group 3 of 6, group 1 being the genes least tolerant of losing a copy. Missense variants: 287 observed, 270.76 expected, observed/expected ratio (o/e) 1.06, 90% interval 0.96 to 1.17. Synonymous variants: 113 observed, 100.04 expected, observed/expected ratio (o/e) 1.13, 90% interval 0.97 to 1.32.
Homologues: Orthologues: macaque EMB (94% identical), chimpanzee EMB (88% identical), pig EMB (77% identical), rabbit EMB (67% identical), rat Emb (67% identical), mouse Emb (65% identical), guinea pig EMB (61% identical), dog EMB (60% identical), tropical clawed frog emb (34% identical), zebrafish emb (31% identical), Drosophila melanogaster Bsg (18% identical), Caenorhabditis elegans zig-11 (14% identical). Paralogues in human: NPTN (23% identical), BSG (22% identical), VSTM2L (9% identical).
Diseases named in the same sentence as EMB in open-access papers:
EMB is named in the same sentence as 32 diseases in open-access papers, as found by Europe PMC text mining. Sharing a sentence is not in itself a finding about the gene and the disease. The quoted sentences say what the papers report.
breast cancer (11 papers, 2015 to 2025). A primary or metastatic malignant neoplasm involving the breast. "Studies have linked embigin to pancreatic adenocarcinoma and breast cancer, with both organs containing sebaceous glands." (PMID 38446446, 2024). "Previously we demonstrated that high expression of HOXC8 was significantly associated with low recurrence-free survival rate of breast cancer patients, so we evaluated the correlation between embigin expression and breast tumor recurrence." (PMID 26090721, 2015). "In this study, we show that HOXC8 binds to the embigin promoter and transcriptionally inhibits embigin expression, and loss of embigin expression enhances proliferation, anchorage-independent cell growth, and migration of breast cancer cells and normal breast cell MCF10A." (PMID 26090721, 2015). "Taken together, these data suggest that embigin loss promotes breast cancer development, and may play a particularly important role in the progression of basal-like tumors." (PMID 26090721, 2015). "Embigin (EMB), a transmembrane glycoprotein of the immunoglobulin superfamily, is involved in the occurrence and development of prostate cancer, pancreatic cancer and breast cancer, and is associated with poor prognosis in cancer patients, but not in reports of gastric cancer." (PMID 37066015, 2023). "Later studies showed that HOXC8 is involved in breast cancer progression by either transcriptionally upregulating cadherin-11 expression or acting as a transcriptional repressor of the tumor suppressor Embigin." (PMID 40701951, 2025). "Embigin suppresses tumorigenesis in breast cancer cells while promoting pancreatic cancer progression." (PMID 38446446, 2024). "In this study, we show that embigin is transcriptionally regulated by Homeobox C8 (HOXC8) in breast cancer cells and embigin expression suppresses breast tumorigenesis." (PMID 26090721, 2015). "Embigin is expressed in regressing prostate and mammary gland and also detected in prostate and mammary cancer cell lines, but very little is known about its function in breast cancer cells." (PMID 26090721, 2015). "To validate the roles of embigin in breast cancer progression, we further analyzed embigin expression in different breast cancer subtypes." (PMID 26090721, 2015). "The present study shows, for the first time, that embigin plays a suppressive role in breast cancer progression, particularly in basal-like tumors." (PMID 26090721, 2015). "Taken together, these data show that HOXC8 is involved in regulation of embigin expression in breast cancer cells." (PMID 26090721, 2015). "It has been reported that embigin protein is expressed in a variety of prostate and mammary cancer cell lines, and its expression appears to be down-regulated in cancer cells upon Matrigel culture." (PMID 26090721, 2015). "We initially demonstrated that HOXC8 functions as a transcription factor to inhibit embigin transcription, and embigin knockdown enhances the proliferation, anchorage-independent growth and migration of breast cancer cells and normal breast cells." (PMID 26090721, 2015). "To determine the function of embigin in breast cancer cells, we analyzed the effect of embigin on cell proliferation, anchorage-independent cell growth and cell migration in MDA-MB-231 and MCF7 cells." (PMID 26090721, 2015). "HOXC8 knockdown mediated inhibition on breast cancer cell growth and migration can be reversed largely by removal of embigin protein expression, indicating the functional linking between embigin and HOXC8 in breast tumorigenesis." (PMID 26090721, 2015). "In conclusion, this study demonstrates that embigin is transcriptionally regulated by HOXC8 protein and its low/loss expression may play an important role in the progression of breast cancers." (PMID 26090721, 2015). "Furthermore, transwell assay showed that embigin overexpression inhibited cell migration, and embigin knockdown enhanced the migration of breast cancer cells." (PMID 26090721, 2015).
breast cancer (continued). "Our data indicate that embigin could be useful as a prognostic biomarker in breast cancers, at least the subset of breast basal-like cancers, although our observations do not preclude its potential involvement in other subtypes." (PMID 26090721, 2015). "Among those genes, we are interested in examining whether HOXC8 is involved in regulating embigin expression in breast cancer cells." (PMID 26090721, 2015). "More importantly, depletion of HOXC8 leads to significant reduction of proliferation, colony formation and migration of breast cancer cells, which can be largely recovered by embigin knockdown, suggesting the functional linking between HOXC8 and embigin in breast cancer cells." (PMID 26090721, 2015). "Based on these findings, we hypothesize that HOXC8 regulates various genes transcription in breast cancer development, which includes activating cadherin-11 and inhibiting embigin transcription in breast cancer cells." (PMID 26090721, 2015). "Previous studies have reported an increased expression of HOXC8 during breast cancer progression that can induce metastasis through direct regulation of CDH11 and EMB genes." (PMID 28202042, 2017). "Taken together, our results showed that embigin is transcriptionally regulated by HOXC8 protein, and plays a suppressive role in breast cancer progression." (PMID 26090721, 2015). "Taken together, these results show that inhibitory effects of embigin on cell proliferation, anchorage-independent growth and cell migration are functionally regulated, at least in part, by HOXC8 protein in breast cancer cells." (PMID 26090721, 2015). "Previously we reported that HOXC8 mediates proliferation, migration and metastasis of breast cancer cells, it is interesting to explore whether HOXC8 affects these behaviors by regulating embigin transcription." (PMID 26090721, 2015). "Embigin is also detected in cancer cell lines, such as breast cancer cells MDA-MB-231 and MCF7, and its expression is decreased upon culture in Matrigel, indicating embigin may play a role in breast tumorigenesis." (PMID 26090721, 2015).
prostate carcinoma (7 papers, 2009 to 2023). A carcinoma that arises from epithelial cells of the prostate gland. "This prompted us to disclose another role of embigin in promoting prostate cancer cells in association with extracellular S100A4." (PMID 30041429, 2018). "S100A4 binding to embigin spesifically augments prostate cancer sell migration, which partly due to inhibition of AMPK activity." (PMID 30041429, 2018). "We further investigated the clinical relevance of embigin and its downstream-mediated signaling in prostate cancer progression by using SurvExpress." (PMID 30041429, 2018). "Throughout this study, we focused on DU145 cells to clarify the unidentified role of embigin in prostate cancer progression as those cells showed the highest embigin expression at both mRNA and protein levels." (PMID 30041429, 2018). "We next investigated the importance of the embigin cytoplasmic tail for mediating intracellular downstream signals in prostate cancer progression." (PMID 30041429, 2018). "We found that pancreatic and prostate cancer cell lines consistently expressed embigin mRNA at levels that were more than 3-fold higher than the level in normal fibroblast cells." (PMID 30041429, 2018). "Our results showed that embigin induces prostate cancer cells migration and activation of NF-κB, and MMP9 activation and that the migration was enhanced by extracellular S100A4." (PMID 30041429, 2018). "In the present study, we found that S100A4 binding to embigin mediate prostate cancer migration partly through down-regulation of AMPK activity." (PMID 30041429, 2018). "Embigin also promotes prostate cancer growth, spheroid-and colony-forming ability, and survival upon chemotherapy independently of S100A4." (PMID 30041429, 2018). "Binding of extracellular S100A4 to embigin mediates prostate cancer progression by inhibition of AMPK activity, activation of NF-κB, MMP9 and mTORC1 signaling, and inhibition of autophagy, which increase prostate cancer cell motility." (PMID 30041429, 2018). "PK-8 cells for pancreatic cancer cells and DU145 cells for prostate cancer cells also produced embigin protein at markedly higher levels." (PMID 30041429, 2018). "We also found that embigin promotes prostate cancer growth, spheroid- and colony-forming ability, and survival upon chemotherapy independently of S100A4." (PMID 30041429, 2018). "We have shown that embigin contributes to the progression of prostate cancer with multiple cancer behaviors through AMPK/mTORC1/p21WAF1 and NF-κB/MMP9 signaling." (PMID 30041429, 2018). "Finally, survival analysis using publicly available data revealed that embigin and p21WAF1 provide potential benefit as prognostic biomarkers for prostate cancer patients." (PMID 30041429, 2018). "The intracellular cytoplasmic tail of embigin is vital for prostate cancer cell proliferation." (PMID 30041429, 2018). "This suggests embigin might affect prostate cancer growth by its interaction with either MCT2 or other MCTs that reprogram cancer metabolic activity independently to S100A4." (PMID 30041429, 2018). "Additionally, as our data have shown, embigin and p21WAF1 can be used as prognostic biomarkers for prostate cancer patients." (PMID 30041429, 2018). "The binding of extracellular S100A4 to embigin mediates prostate cancer progression by orchestrating multiple mechanisms including inhibition of AMPK activity, activation of NF-κB, MMP9, and mTORC1 signaling, and inhibition of autophagy, which lead to an increase in cellular motility." (PMID 30041429, 2018). "Therefore, this study aims to identify a specific ligand for embigin and its roles in prostate cancer progression." (PMID 30041429, 2018). "We hence hypothesized that embigin plays a critical role in survival of prostate cancer cells during docetaxel treatment." (PMID 30041429, 2018).
prostate carcinoma (continued). "To determine other possible functions of embigin that are relevant to prostate cancer aggressiveness, we performed comprehensive gene expression analysis of DU145 cells stably overexpressing embigin in comparison to GFP-control cells by using an RNA-sequencing technique." (PMID 30041429, 2018). "Therefore, targeting S100A4/embigin-mediated signaling is a potential prostate cancer therapeutic approach for prostate cancer patients." (PMID 30041429, 2018). "Therefore, targeting S100A4/embigin is a promising therapeutic strategy for prostate cancer." (PMID 30041429, 2018). "Moreover, embigin and p21WAF1 can be used to predict survival of prostate cancer patients." (PMID 30041429, 2018). "Almost the same patterns of molecular signaling were also observed in both the LNCaP prostate cancer cell line in a transient expression system and the DU145 subline with stable expression of exogenous embigin." (PMID 30041429, 2018). "Embigin expression is significantly high in DU145 cells, which is one of the androgen-independent prostate cancer cell lines with brain metastasis." (PMID 30041429, 2018). "Our results demonstrated for the first time that the S100A4-embigin/AMPK/mTORC1/p21WAF1 and NF-κB/MMP9 axis is a vital oncogenic molecular cascade for prostate cancer progression." (PMID 30041429, 2018). "S100A4 binding contributes mainly to the migration process, suggesting that overexpressed embigin in cancer cells and S100A4 in the surrounding stroma are coordinately functional for prostate cancer progression." (PMID 30041429, 2018). "We propose that the S100A4-embigin/AMPK/mTORC1/p21WAF1 and NF-κB/MMP9 axis is a vital oncogenic molecular machinery exploited by a certain fraction of prostate cancers for progression." (PMID 30041429, 2018). "As embigin’s roles in cancer remain elusive, we studied its biological functions and interaction with extracellular S100A4 in prostate cancer progression." (PMID 30041429, 2018). "However, S100A4 binding does not contribute to the embigin-mediated invasion of prostate cancer cells." (PMID 30041429, 2018). "However, S100A4 binding to embigin did not further induce growth of prostate cancer cells." (PMID 30041429, 2018).
leukemia (6 papers, 2010 to 2021). A malignant (clonal) hematologic disorder, involving hematopoietic stem cells and characterized by the presence of primitive or atypical myeloid or lymphoid cells in the bone marrow and the blood. "With respect to EMB (XPO1 in mammals) and RAE1, their mammalian homologs have been shown to contribute to NA9-induced leukemia through their association with the FG / GLFG motifs and GLEBS domain of NA9, respectively, which appears to interfere with nucleocytoplasmic transport." (PMID 34383740, 2021). "Concordantly, the expression of surface proteins (CX3CR1, CXCR4, EMB, ITGB4, LSP, VCAM1) important for leukemia infiltration was downregulated in IGFBP2-null bone marrow AML cells." (PMID 24191913, 2013).
glioma (2 papers, 2019 to 2022). A benign or malignant brain and spinal cord tumor that arises from glial cells (astrocytes, oligodendrocytes, ependymal cells). "The expression levels of EMB, LDHA, SLC16A1, SLC16A3, SLC16A8, PARK7, and PFKFB2 were lower in 1p/19q Codel glioma than those in non-Codel glioma." (PMID 36698888, 2022).
hearing loss (2 papers, 2022 to 2023). "Embigin (Emb) was previously reported as a candidate novel gene for hearing loss." (PMID 37854703, 2023). "Notably, Embigin was also identified as a hearing loss candidate gene by the IMPC programme." (PMID 35100259, 2022). "The Embigin gene (Emb) encodes a highly glycosylated protein belonging to a small subgroup of immunoglobulin neural cell adhesion molecules alongside Basigin (Bsg, also known as CD147) and Neuroplastin (Nptn), the latter of which has recently been linked to early onset hearing loss in mice." (PMID 37854703, 2023).
pancreatic cancer (2 papers, 2018 to 2023). "Embigin expression has been reported to suppress tumorigenesis in breast cancer cells, while it promotes pancreatic cancer progression." (PMID 30041429, 2018). "A recent study also showed that embigin positively regulates cellular motility, MMP secretion, and TGF-β downstream signaling in pancreatic cancer." (PMID 30041429, 2018).
breast tumor (1 paper, 2015). "Taken together, our study demonstrates that low/loss of embigin plays an important role in the progression of breast tumors." (PMID 26090721, 2015).
gastric cancer (1 paper, 2023). A primary or metastatic malignant neoplasm involving the stomach. "In this study, the gastric cancer patients with high expression of CTLA4 and ENTPD2 had a better survival prognosis, with high expression of CLDN6, EMB, GPR15, VWF and AKR1B1 suggesting poor prognosis, which was consistent with previous studies." (PMID 37066015, 2023).
gastric tumor (1 paper, 2023). "Compared with benign tissues, the CTLA4 and ENTPD2 were highly expressed in gastric tumor tissues, while the AKR1B1, CLDN6, EMB, GPR15 and VWF were highly expressed." (PMID 37066015, 2023).
prostate tumor (1 paper, 2018). "An in vivo growth mouse model confirmed the importance of embigin and its cytoplasmic tail in mediating prostate tumor growth." (PMID 30041429, 2018).